TF (transferrin)
Diseases named in the same sentence as TF in open-access papers (continued):
Sharing a sentence is not in itself a finding about the gene and the disease.
type 2 diabetes (27 papers, 2009 to 2025). "Elevated ferritin and transferrin values, even below those seen in hemochromatosis, and iron overload are also associated with abnormal glucose metabolism and insulin resistance in type 2 diabetes." (PMID 39201524, 2024). "The phenolic compounds in berry and citrus can be interacted directly with the dimerization domains of hepatocyte nuclear factor-1α (HNF-1α, a TF supporting the transcription of proteins linked with type II diabetes)." (PMID 36837850, 2023). "A clinical longitudinal retrospective study reported on an association between lower serum transferrin concentration and end-stage diabetic nephropathy in patients with type 2 diabetes." (PMID 36401188, 2022). "TF can repress alkaline phosphatase activities in osteoblasts due to high oxidative stress, and increased TF expression increases the risk of type 1 and/or type 2 diabetes." (PMID 35328013, 2022). "It has been reported that patients with high serum transferrin are at higher risk of type 2 diabetes." (PMID 33633672, 2021). "The clinical relevance of free iron in severe malaria infections has been investigated previously, and high transferrin saturation (which indicates mobilization of ferrous iron) was associated with delayed recovery from coma in CM patients." (PMID 22438807, 2012). "Ferritin and transferrin saturation are associated with increased risk of type 2 diabetes." (PMID 40871742, 2025). "In 59 to 92% of patients with type 2 diabetes, excess amounts of non-transferrin-bound iron, forming the intracellular LIP, are correlated with the severity of the disease." (PMID 39201524, 2024). "The urinary transferrin and RBP and serum osteopontin, had the best diagnostic value in type 2 diabetic patients at different stages of diabetic nephropathy." (PMID 28577020, 2017). "In type 1 and type 2 diabetes, and even among diabetic complications, most patients have abnormal iron metabolism, manifested by serum iron (SI), ferritin (SF), and transferrin saturation (TS) levels that are significantly higher than in the general population." (PMID 37077360, 2023). "The iron ions released by TF exacerbate cellular oxidative stress and insulin resistance in patients with type 2 diabetes mellitus (T2DM)." (PMID 40092979, 2025). "For example, BRX-0585, a transferrin-glucagon-like peptide-1 (GLP-1) fusion protein for the treatment of type 2 diabetes mellitus (T2DM), demonstrated significantly enhanced half-life." (PMID 36393853, 2022). "Furthermore, increased urinary transferrin excretion predicts the development of microalbuminuria in type 2 diabetic patients with normoalbuminuria; in patients that already developed albuminuria, the urinary transferrin excretion has a linear relationship with UAE." (PMID 22645683, 2012). "Non-transferrin-bound iron is also considerably elevated in type 2 diabetes, and this too is exacerbated by vitamin C. Iron metabolism is substantially deranged in type 2 diabetes and the metabolism of glucose (a reducing sugar) interacts significantly with iron metabolism." (PMID 19133145, 2009). "The KORA F4 study has found that high ferritin and transferrin levels and low soluble transferrin receptors are independently related to impaired glucose metabolism (IGM) and type 2 diabetes mellitus (T2DM; 12)." (PMID 35911095, 2022). "In patients with type 2 diabetes and CKD, a post hoc analysis of the DELIGHT trial reported that changes in TSAT and transferrin over 24 weeks of treatment with dapagliflozin correlated with changes in urinary and plasma interleukin-6, an inflammatory cytokine that regulates hepcidin expression." (PMID 39304530, 2025). "Among type 2 diabetic patients, urinary transferrin significantly increases with respect to the progress of biopsy proven glomerular diffuse lesions and has been shown that some type 2 diabetic patients with diffuse glomerular lesions without microalbuminuria had microtransferrinuria." (PMID 22645683, 2012).
brain tumor (26 papers, 2013 to 2025). "We find that the variability in the in vivo r1-r2* relaxivity of brain tumors is explained by their transferrin-ferritin ratios and is associated with iron-related genes." (PMID 37699931, 2023). "Consistent with this hypothesis, the researcher observed that treatment with TMZ-JQ1 transferrin linked liposomes enhanced the brain tumor localization of both drugs and increased survival rates in mouse xenograft models relative to single drug administration." (PMID 38542190, 2024). "However, a lower baseline level of tissue factor activity related to MPs in GBM cohorts or the expression of brain tumor-associated TF is indirectly associated with VTE." (PMID 38001743, 2023). "With surface modification, CNPs can carry tumor-targeting peptides such as transferrin and chlorotoxin, which increase their selectivity and specificity to brain tumors." (PMID 41304419, 2025). "The levels of transferrin are elevated in malignant brain tumors, which can be exploited for targeted drug delivery." (PMID 38542190, 2024). "For example, a study compared the BBB penetration and brain tumor accumulation of transferrin-functionalized gold NPs and TAT-conjugated gold NPs, demonstrating the superior performance of the transferrin-targeted NPs." (PMID 39021831, 2024). "In this study, we designed a series of peptide-based gene delivery vectors decorated with T7 segment for binding the transferrin (Tf) receptors which were highly expressed on brain tumor cells, and evaluated their ability of gene delivery." (PMID 35866298, 2022). "The present data have showed that serum TF-UP/LRP level in patients with acute ischemic stroke was lower than those in patients with brain tumors." (PMID 33633672, 2021). "In conjugation with various nanomaterials, transferrin as efficient moiety for imaging and therapy of brain tumors has been extensively verified." (PMID 31619957, 2019). "In another study, the iron-transport protein transferrin was labeled with 89Zr to be applied in brain tumor imaging as well as in imaging of transferrin receptor expression." (PMID 23736785, 2013). "The successful permeation of TF-Cur-Nio across the BBB highlights its potential in targeted cancer therapy, particularly in overcoming the challenges associated with BBB penetration for brain tumor treatment." (PMID 40140588, 2025). "Interestingly, CQD-based NPs functionalized with transferrin and loaded with chemotherapeutic drug doxorubicin elicited excellent cytotoxic effects against pediatric brain tumor cells in vitro." (PMID 36358807, 2022). "Moreover, surface modification of chitosan-based NPs, e.g., by functionalization with transferrin, apoE or chlorotoxin, can improve brain tumor targeting." (PMID 36358807, 2022). "An appropriate example is the transferrin-based NPs that have elicited tremendous abilities to cross the BBB/BBTB by targeting the transferrin receptor-mediated transcytosis (see also Section 4.4.1) for brain tumor therapy." (PMID 36358807, 2022). "Nevertheless, several studies proposed that 99mTc-TF might be superior to 99mTc-MIBI for brain tumor imaging, since the latter is influenced to a greater degree by tumor's multidrug resistance phenotype (MDR)." (PMID 25436147, 2014). "NPs in the size range of 20–100 nm, with neutral or slightly negative surface charge, and functionalized with targeting ligands such as transferrin or peptides, have shown promise in traversing the BBB and delivering therapeutic agents to brain tumors." (PMID 39021831, 2024). "99mTc-Tetrofosmin (99mTc-TF) and 99mTc-sestamibi (99mTc-MIBI) are tracers that have been used among others for brain tumor imaging." (PMID 25436147, 2014). "Unlike transferrin, T7 peptide can specifically bind to TfR, enhancing the ability of drugs to penetrate brain tumor cells with its small molecular weight and high targeting specificity." (PMID 40142943, 2025).
brain tumor (continued). "When examining the TF enrichment results in the categorized GTRD data, all the EZH2 binding sites, but those originating from other brain tumors, were enriched in AT/RT-hyper regions, including EZH2 binding sites in neural progenitors and more differentiated neural samples." (PMID 38499326, 2024). "Similarly, PEGylated liposomes containing QDs along with the chemotherapeutic agent docetaxel can be synthesized and coated with transferrin to improve permeability across the BBB, allowing treatment of brain tumors while monitoring liposomal distribution." (PMID 35456971, 2022). "Serum TF-UP/LRP ratio is a more sensitive and more specific biomarker for neural damage in acute ischemic stroke than Alb-UP/LRP ratio and TF-UP/Alb-UP ratio, in comparison with brain tumors." (PMID 33633672, 2021). "The hypothesis that hepcidin value changes in brain tumors has emerged in comparison with the corresponding normal tissues, according to variation of other parameters such as, HFE, neogenin (NEO1), receptor 1 for transferrin (TFR) and receptor 2 for transferrin (TFR2)." (PMID 24146699, 2013).
hepatocellular carcinoma (25 papers, 1972 to 2026). A malignant tumor that arises from hepatocytes. "DOX was also loaded onto BMNs together with transferrin (Tf) and tested in human liver carcinoma cells (HepG2)." (PMID 36827100, 2023). "Compared with free TP and non-targeted TP liposomes, the addition of TF significantly enhanced hepatoma cell cytotoxicity, as well as showed enhanced uptake of the TF-TP@LIP in vitro." (PMID 37893242, 2023). "Classic experiments conducted 40 years ago gave an exquisite account of the kinetics of the internalization of transferrin and the transferrin receptor in a human hepatoma cell line 47,48." (PMID 37286800, 2023). "Dual‐specificity tyrosine (Y) phosphorylation‐regulated kinase (DYRK) 3 reprograms purine synthesis by blocking NCOA3/ATF4 TF complex in hepatocellular carcinoma." (PMID 35092699, 2022). "Surface modification with transferrin enabled the nanoplatform to target the overexpressed transferrin receptors in hepatocellular carcinoma (HCC) cells and facilitate tumor accumulation as well as intracellular DOX delivery." (PMID 36080059, 2022). "The results showed that a total of 52 transcription factors have significant transcriptional regulation on hepatocellular carcinoma dysfunction modules, involving 52 TF-Module regulatory pairs." (PMID 34651050, 2021). "Depending on the predictive analysis of multidimensional regulators, 323 ncRNAs and 52 TF-mediated hepatocellular carcinoma-related dysregulation modules were found to regulate disease progression." (PMID 34651050, 2021). "HNF4α has been shown to control iron homeostasis in liver and hepatoma cells through the regulation of transferrin, transferrin receptor-1 and hepcidin genes." (PMID 31532389, 2019). "The effects of TF on the body weight, tumor growth volume and tumor inhibition rate were observed in nude mice model of human hepatocellular carcinoma by vivo experiments." (PMID 28903343, 2017). "The inclusion of TF also increased cell cycle arrest and promoted apoptosis in hepatoma cells." (PMID 37893242, 2023). "The transferrin arc from liver, plasma and hepatoma had identical mobility." (PMID 4340062, 1972). "In this study, a TF-modified liposome, targeting the TFR on the surface of hepatocellular carcinoma cells, was designed for the delivery of TP." (PMID 37893242, 2023). "In the regulation of transcription factors, STAT6 essentially regulates two functional disorder modules, while TF such as AR and ATF2 has a driving effect on one module, which affects the occurrence and development of hepatocellular carcinoma." (PMID 34651050, 2021). "In human hepatoma HepG2 cell line curdlan sulphate enhances basal and interleukin-6-stimulated fibrinogen and antichymotrypsin (ACT) synthesis, slightly increases basal ceruloplasmin production and exerts only minor effects on alpha-1-proteinase inhibitor and transferrin." (PMID 18472835, 1997).
Stroke (25 papers, 2011 to 2025). Sudden impairment of blood flow to a part of the brain due to occlusion or rupture of an artery to the brain. "Conversely, genetically predicted higher transferrin saturation was nominally associated with higher risk of stroke." (PMID 34899831, 2021). "This association is thought to be particularly vulnerable to selection bias, especially among older populations, because transferrin affects survival and stroke is open to competing risk from IHD." (PMID 34899831, 2021). "A higher transferrin, indicative of lower iron status, was also associated with decreased stroke risk (OR, 0.92; 95% CI, 0.86–0.99)." (PMID 30571402, 2018). "Along this line, platelet and SMC-derived TF+-cMPs were significantly elevated compared to controls in the three time points, partially explaining the increased risk of recurrent stroke in those patients." (PMID 26815842, 2016). "Furthermore, the Mendelian randomization technique provided evidence that higher iron status, manifested as elevated SF concentration and transferrin saturation, is associated with increased stroke risk." (PMID 35067842, 2022). "For example, previous observational studies showed that higher transferrin binds to circulating iron and influences iron status, which may further cause iron-deficiency anemia and increase the risk of stroke." (PMID 34899831, 2021). "We focus on plausible causal structures relevant to MR studies and illustrate how to validate MR estimates using control exposures through a real example investigating the potential association of transferrin with stroke (including ischemic and cardioembolic stroke)." (PMID 34899831, 2021). "In addition, a higher transferrin, indicative of a lower iron status, was associated with a decreased stroke risk (OR, 0.92; 95% CI, 0.86–0.99; P=0.02)." (PMID 30571402, 2018). "Finally, iron, ferritin, and transferrin saturation, biomarkers of iron metabolism and intake, showed robust positive causal associations with risk of stroke in MR analyses and this effect was suggested to be driven by an increased risk of cardioembolic stroke." (PMID 37804188, 2023). "Of particular interest in developing therapeutics to promote neural repair, a number of groups have validated the feasibility of ectopic TF expression in preclinical models of injury and disease, including Alzheimer’s disease, Parkinson’s disease, and stroke." (PMID 38540276, 2024). "We have previously demonstrated that the post-stroke administration of iron-free transferrin (apotransferrin, ATf) is beneficial in different models of ischemic stroke (IS) through the inhibition of the neuronal uptake of pro-oxidant iron." (PMID 38001798, 2023). "In a case-control study, lower level of TF and higher level of ferritin were found in the serum of 42 stroke patients, compared with 62 healthy controls." (PMID 33633672, 2021). "Our applied example showing inconsistent effects of genetically predicted higher transferrin and higher transferrin saturation on stroke suggests the potential selection bias." (PMID 34899831, 2021). "We apply the proposal in an MR study investigating the potential effect of higher transferrin with stroke (including ischemic and cardioembolic stroke) using transferrin saturation and iron status as control exposures." (PMID 34899831, 2021). "Tar-exo-enkephalin using transferrin and enkephalin represents an innovative structure and approach in the treatment for stroke." (PMID 30949500, 2019). "Baseline characteristics were similar across two arms except higher serum ferritin, transferrin saturation and prevalence of stroke in D2 and higher coronary artery disease in control group with overall mean ± SD 25(OH)D level of 16.8 ± 7 ng/ml." (PMID 27717322, 2016). "Further, the previous stroke study used the ubiquitous CAG promotor to drive TF expression." (PMID 38540276, 2024).
Stroke (continued). "Serum albumin, prealbumin, and transferrin levels were associated with ANS function, as measured by HRV, and their deficiency may be a predictive factor for the severity of ANS dysfunction in stroke patients." (PMID 36558479, 2022). "Fasted blood concentrations of vitamins B1, B2, B6, A, D, and E, selenium, choline, coenzyme Q10, albumin, pre-albumin, transferrin, docosahexaenoic acid, and eicosapentaenoic acid were all lower in stroke patients compared to their matched healthy reference subjects, irrespective of OD status." (PMID 36703642, 2022). "Finally, the consistent effects of higher transferrin saturation and higher iron status on stroke and longevity further triangulated our conclusions." (PMID 34899831, 2021). "The decreased levels of both LINGO1 and NOGO-A might initially seem to be due to a lower number of OPCs and also OLCs, but the transferrin gene (TF), which is only found in oligodendrocytes in the adult brain, was upregulated at both 24 h and 3 d after stroke." (PMID 23284893, 2012). "Although high TF expression in the brain could in part account for thrombotic stroke consequences, it certainly warrants investigation to explore if TF and its signaling participate in other neuronal dysfunctions or CNS disorders." (PMID 21941675, 2011). "Stroke showed a somewhat different profile of associations, with evidence for causal effect for thrombotic risk factors (factor VII, factor XI, platelet count, vitamin K), iron and inflammatory biomarkers (iron, transferrin, transferrin saturation, IL6R), and blood pressure." (PMID 37804188, 2023). "Alterations of nutritional status have been described in stroke patients in terms of body composition (i.e., fat-free mass or calf circumference), energy expenditure, and laboratory tests (for instance, vitamin status and plasma proteins such as transferrin and transthyretin)." (PMID 36771390, 2023). "Even if selection bias exists, its impact on the transferrin saturation–stroke and iron status–stroke associations would be limited or at least could not reverse the observed associations or biased them to the null." (PMID 34899831, 2021). "This will give a clue of whether TF-UP levels reduce in a time-dependent manner post-stroke onset." (PMID 33633672, 2021). "One reason is that whilst ferritin is known to release free iron into the brain parenchyma after stroke‐induced injury of the BBB, another iron carrier, transferrin, can reduce iron availability and mitigate ischaemic injury." (PMID 39460712, 2025). "Last, the stroke rate across the whole study population was reasonably low and, despite not reaching statistical significance, TCAR appeared to have the lowest stroke rate (1.7% vs 2.1% for CEA and 3.6% for TF-CAS)." (PMID 37852227, 2024). "Stroke patients had lower levels of serum transferrin, pre-albumin, and albumin compared to HR subjects, and in turn were lower in stroke patients with OD vs. patients without OD." (PMID 36703642, 2022). "Fasted blood concentrations of vitamins B1, B2, B6, A, D, and E, selenium, choline, CoQ10, albumin, pre-albumin, transferrin, DHA, EPA, LA, and ALA were all significantly lower in stroke compared to age- and sex-matched matched HR subjects, irrespective of OD status." (PMID 36703642, 2022). "Surprisingly, we observed that at the onset of stroke and after 7 days, SMC-derived cMPs (but not SMC-derived MPs carrying TF) were similar to the levels observed in non-CVD controls." (PMID 26815842, 2016).